Y_RNA (Y RNA )
Gene: Miscellaneous RNA gene on chromosome 22 (20,481,158 to 20,481,268, forward strand). Ensembl gene ENSG00000201916.
Homologues: Orthologues: chimpanzee Y_RNA (99% identical), macaque Y_RNA (86% identical). Paralogues in human: RNY1 (84% identical), RNY1P11 (84% identical), Y_RNA (83% identical), Y_RNA (82% identical), Y_RNA (81% identical), RNY1P10 (80% identical), RNY1P5 (80% identical), RNY1P8 (80% identical), Y_RNA (80% identical), RNY1P7 (79% identical), Y_RNA (79% identical), Y_RNA (78% identical), and 94 more.